PBX3 (PBX homeobox 3)
Diseases named in the same sentence as PBX3 in open-access papers (continued):
Sharing a sentence is not in itself a finding about the gene and the disease.
tumor (continued). "Furthermore, our results suggested that PBX3 is a potential target for metabolic-based anti-tumor therapeutic strategies." (PMID 37781025, 2023). "Despite accumulating evidence showing its oncogenic role, whether PBX3 is involved in tumor cell metabolic reprogramming remains unknown." (PMID 37781025, 2023). "MiR-4458 tumor inhibition features occurred via binding with PBX3 3′-UTR." (PMID 36982460, 2023). "The tumor-suppressing effect of miR-458 was suppressed through the upregulation of PBX3." (PMID 36982460, 2023). "Together, our study unravels a novel function of PBX3 in regulating tumor metabolic reprogramming." (PMID 37781025, 2023). "Knockdown of circNRIP1 attenuated the PTC tumor progression via miR-653-5p/PBX3 axis." (PMID 35646117, 2022). "Additionally, PBX3 was a key factor for HCC tumour‐initiating cells (TICs) to acquire and maintain their properties." (PMID 35068042, 2022). "In addition, overexpression of PBX3 reversed the role of silencing of circNRIP1 on the apoptosis of tumor cells indicated by Tunel assay." (PMID 35646117, 2022). "In addition, circNRIP1 and PBX3 expression decreased while miR-653-5p expression increased in tumor tissues under circNRIP1 knockdown." (PMID 35646117, 2022). "Let‐7c, miR‐200b, miR‐222 and miR‐424 synergistically target PBX3 in HCC tumour‐initiating cells." (PMID 35068042, 2022). "The expression of PBX3 was noticeably high in tumor tissues." (PMID 32519740, 2020). "Let-7c acted as a tumor inhibitor via depleting the expression level of PBX3." (PMID 32519740, 2020). "miR-495 acts as a tumor suppressor by directly targeting and downregulating Pbx3." (PMID 33402862, 2020). "Decreased levels of miR-320a in CAF-derived exosomes promote cell proliferation, migration, and metastasis; loss of miR-320a leads to de-repression of its target PBX3, activating MAPK pathway and up-regulation of CDK2 and MMP2; in vivo, miR-320a overexpression suppresses tumor growth and metastasis." (PMID 32957712, 2020). "In addition, PBX3 depletion reduced tumor growth and resulted in the formation of significantly smaller tumors when compared with the control group." (PMID 30016974, 2018). "According to the previous literatures, PBX3 is essential for the acquisition and maintenance of the liver tumor-initiating cells properties, which is generally considered to be closely correlated with tumor migration and metastasis." (PMID 27285759, 2016). "Furthermore, rescue experiments by over-expression PBX3 completely eliminated the inhibitory effects of miR-33a-3p on tumor growth and metastasis, both in vitro and in vivo." (PMID 27285759, 2016). "Together, these results indicate that PBX3 might promote tumor cell lipid metabolism." (PMID 40508020, 2025). "PBX3 could also promote the expression of Bcl-2, leading to the decrease in tumor cell apoptosis." (PMID 40508020, 2025). "Moreover, the expression level of PBX3 was related to tumor grade and pathological stage." (PMID 38324550, 2024). "Together, these results indicate that PBX3 might be involved in tumor cell glucose metabolism." (PMID 37781025, 2023). "Thus, although further investigations are needed, PBX3 regulation in tumor metabolic reprogramming, and subsequently, tumorigenesis, might involve multiple pathways." (PMID 37781025, 2023). "Interestingly, EVs mediated miR-320a could function as anti-tumor miRNAs by binding to its direct downstream target PBX3 to suppress HCC cell proliferation, migration and metastasis." (PMID 29740327, 2018). "However, the molecular mechanisms responsible for the tumor promoting effect of PBX3 are largely unknown." (PMID 28934982, 2017). "However, the role of PBX3 in tumor cell lipid metabolism remains unclear." (PMID 40508020, 2025). "In summary, our findings reveal a new regulatory role of PBX3 in modulating HMGCR expression in HCC cells, establishing a connection between the oncogenic activity of PBX3 and tumor cell lipid metabolic reprogramming." (PMID 40508020, 2025).
tumor (continued). "Moreover, PBX3 could promote the expression of angiogenic factors, such as vascular endothelial growth factor and platelet-derived growth factor, thereby facilitating tumor angiogenesis." (PMID 40508020, 2025). "Together, these results suggest that PBX3 is a positive regulator of G6PD and is crucial for glucose metabolic reprogramming in tumor cells." (PMID 37781025, 2023). "Collectively, these findings reveal a novel function of PBX3 as a regulator of G6PD, linking its oncogenic activity with tumor cell metabolic reprogramming, especially PPP." (PMID 37781025, 2023). "This miRNA targets oncogenes and important genes for the initiation and progression of the tumor, including Myc, RAS, E2F1, E2F5, LIN28, ARID3B, PBX3, HMGA2 and long non-coding RNA H19." (PMID 36833380, 2023). "The expression of both PBX3 and G6PD mRNA in tumor lesions increased significantly compared to adjacent tissues." (PMID 37781025, 2023). "Functionally, we first demonstrated the tumor-suppressive role of miR-516a-5p in HCC both in vitro and in vivo and identified PBX3 as a novel target of miR-516a-5p via its binding to the 3′-UTR of the PBX3 mRNA in HCC cells." (PMID 35509064, 2022). "In tumor-inhibiting conditions, exosomal miR-320a targets PBX Homeobox 3 (PBX3) in recipient cells, resulting in a reduction of phosphor-ERK1/2 and N-cadherin as well, as an increase of E-cadherin." (PMID 32235370, 2020). "Perturbing the PBX3 interaction with HOX or knockdown PBX3 induced apoptosis and inhibited epithelial-to-mesenchymal transition of tumor cells." (PMID 32047817, 2020). "miR-302a is an important regulator of tumor occurrence and deterioration, while MAP3K2 and PBX3 genes are involved in cancer cell proliferation and apoptosis." (PMID 30765768, 2019). "RT-PCR with all four primer combinations—EWSR1-879F/PBX3-1198R1, EWSR1-986F/PBX3-1032R1, EWSR1-879F/PBX3-1032R1, and EWSR1-986F/PBX3-1198R1—amplified cDNA fragments strongly suggesting the presence of an EWSR1-PBX3 fusion transcript in the examined tumor." (PMID 25875009, 2015). "Let-7c was confirmed to have a tumor growth suppressor role but also found to be a tumor metastasis suppressor, which directly destabilizes the mRNA of MMP11 and PBX3 oncogenes." (PMID 23091478, 2012). "Several other authors have confirmed the tumor growth suppression effect of let-7 family members, among them let-7c, which influences MMP11 and PBX3 gene expression." (PMID 23091478, 2012). "Pre-B-cell leukemia transcription factor 3 (PBX3), a member of the PBX family, could promote tumorigenesis; however, whether it is involved in tumor lipid metabolic reprogramming remains unknown." (PMID 40508020, 2025). "One tumor each had an EWSR1::ATF1 (8%) and EWSR1::PBX3 (8%) fusion." (PMID 40748380, 2025). "Furthermore, overexpression of miR-182 inhibits proliferation and induces apoptosis via targeting PBX3 and BCL2, suggesting that miR-182 acts as a tumor suppressor gene in ALL cells." (PMID 38528641, 2024). "Pre-B-cell leukemia transcription factor 3 (PBX3) is a member of the PBX family whose expression is up-regulated in various tumors, however, whether it is involved in tumor cell metabolic reprogramming remains unclear." (PMID 37781025, 2023). "Inhibiting PBX3 could suppress PPP flux, thereby promoting tumor cell antioxidant defenses and proliferation, and subsequently, tumorigenic potential." (PMID 37781025, 2023). "PBX3 could inhibit tumor cell apoptosis by activating the Raf1/MAPK1 pathway 43 and by suppressing tumor suppressor miRNAs, including miR-302, miR-129-5p, and miR-495 34-36." (PMID 37781025, 2023). "Our previous findings demonstrated that positive regulation of G6PD transcriptional activity by various transcription factors (including YY1, NeuroD1, PBX3, and p52-ZER6) enhances tumor cell proliferation by promoting tumor cell nucleotides and lipid biosynthesis." (PMID 38139067, 2023).
tumor (continued). "Moreover, circTOLLIP sponged miR-516a-5p to elevate the expression of PBX3, thereby activating the epithelial-to-mesenchymal transition (EMT) pathway and facilitating tumor progression in HCC." (PMID 35509064, 2022). "Among them, PBX1, PBX2, PBX3 and PBX4, which are members of the PBX gene family, may be involved in tumor cell development." (PMID 33535170, 2021). "Furthermore, knockdown of PBX3 made a significant decrease in endothelial vascular marker CD31 and cell proliferation marker Ki-67 expression in tumor tissues." (PMID 32047817, 2020). "Overexpression of PBX3 without its 3’UTR-let-7c-binding sequence was able to rescue cells from tumor suppressive effects of this miR." (PMID 32069812, 2020). "However, the regulation of PBX3 methylation in CRC and its contribution to tumor progression are still in need of further study." (PMID 31140752, 2019). "Over-expression of miR-33a-3p in HepG2 cells remarkably suppressed not only cell growth, migration and invasion, but also tumor growth and metastases in the chick embryo chorioallantoic membrane (CAM) assay, and down-regulated Pre-B-Cell Leukemia Homeobox 3 (PBX3) expression." (PMID 27285759, 2016). "Furthermore, our in vivo study indicated that the inhibitory effects of miR-33a-3p on tumor growth and metastasis in the CAM model were also counteracted by transfection with PBX3 complementary DNA (cDNA)." (PMID 27285759, 2016). "Moreover, our previous research demonstrated that PBX3 could elevate G6PD expression, which in turn facilitates tumor cell glucose metabolic reprogramming through activating the pentose phosphate pathway." (PMID 40508020, 2025). "Knocking down PBX3 significantly slowed down the growth of the xenografted tumors formed by HCC-LM3 cells, whereas HMGCR overexpression partially reduced this suppressive effect, thus partially restoring the tumor growth rate as well as the size and weight of the tumors." (PMID 40508020, 2025). "Knocking down PBX3 significantly slowed down the growth of the xenografted tumors formed by HCT116p53null cells, whereas G6PD overexpression prevented this suppressive effect, thus restoring the tumor growth rate as well as the size and weight of the generated tumors." (PMID 37781025, 2023). "However, as a miRNA generally has many target genes, whether other targets, such as FAM83D, HOXC6 and PBX3 and MEIS1 we mentioned, are involved in miR-495-mediated anti-tumor activity in NPC is still needed to be clarified." (PMID 35301291, 2022). "Even though the highly expressed miR-144-3p can inhibit the EMT of tumor tissues and cells by targeting EZH2, PBX3, and MAP3K8, we found that EMT could be negatively regulated by miR-144-3p through the ROS/NRF2/Notch1/Snail pathway in high-glucose-stimulated LECs." (PMID 33274006, 2020). "Ra cells were able to initiate tumor formation, whereas under the same condition, no tumorigenicity was detected in the other three samples, which is consistent with the up-regulation of TIC-associated markers in Ra, i.e., CACNA2D1 and PBX3." (PMID 32205176, 2019). "As FOXO1 connects to several of the cancer-associated genes adjacent to PBX3 (though not to PBX3 directly), the relative prominence of both FOXO1 and AKT1 might reflect a potential tumor-inhibiting effect in combination with PBX3 and its neighbors." (PMID 28957313, 2017).
cancer (36 papers, 2011 to 2025). A tumor composed of atypical neoplastic, often pleomorphic cells that invade other tissues. "PBX3 is a cancer-relevant protein that has been reported to be associated with cancer cell metastasis." (PMID 35127685, 2022). "PBX3 is well described as associated with poor prognostic in several cancer types, and the same is correct for GLI3." (PMID 33924679, 2021). "To date, PBX3 is more frequently associated with cancer, and has been reported to be overexpressed in many solid tumors, as well as in several hematological malignancies, where it has a role in promoting cell survival, invasion, and proliferation." (PMID 32069812, 2020). "Here, we review the molecular mechanisms underlying these oncogenic functions in different cancers, and consider the potential of PBX3 as a therapeutic target." (PMID 32069812, 2020). "PBX3 is emerging as a functionally significant transcription factor in a range of cancers, and in the majority of these its expression is linked to aggressive disease and shorter overall survival." (PMID 32069812, 2020). "However, the underlying mechanisms of PBX3 to influence cancer aggressiveness remains to be investigated." (PMID 27285759, 2016). "Aberrant upregulation of PBX3 has been observed in various cancers, including in acute myeloid leukemia and in solid tumors, such as breast cancer, lung cancer, HCC, and colorectal cancer." (PMID 40508020, 2025). "Increasing evidence have elucidated that PBX3 played a crucial role in cancer initiation and progression." (PMID 38324550, 2024). "It is better-known that PBX3 was a cancer-related protein, and it is central to numerous gene molecular networks." (PMID 34001137, 2021). "Pre-leukemia transcription factor 3 (PBX3) is the main mediator in the onset and progression of aggressive phenotypes in human cancers." (PMID 34001137, 2021). "Emerging reports showed that PBX3 is up-regulated in multiple human cancers, including glioblastoma, hepatocellular carcinoma and PCa." (PMID 32519740, 2020). "While this mode of regulation seems to be more relevant to early developmental processes, a number of other mechanisms have emerged as potential, specific regulators of PBX3 in the context of cancer." (PMID 32069812, 2020). "Dysregulation of PBX3 expression has been observed in many cancer types, such as prostate, gastric, cervical, and liver cancer." (PMID 32487167, 2020). "The clear role emerging for PBX3 as a promoter of cell survival, invasion, and metastasis in cancer makes it an attractive therapeutic target." (PMID 32069812, 2020). "In this review we consider the similarities and differences in the function of PBX3 in different cancer types and draw together the core signaling pathways involved to help provide a better insight into its potential as a therapeutic target." (PMID 32069812, 2020). "Combination with ten cancer types in pan-cancer, four mRNAs (PBX3, KLF6, ARHGAP1, ST3GAL2) were selected out." (PMID 32519740, 2020). "In this study, the clinical significance and tumorigenesis of the novel cancer-related transcription fact or PBX3 were investigated for PTC." (PMID 32047817, 2020). "Functional studies revealed that upregulated PBX3 promotes cancer cell malignant behaviors, such as proliferation, migration, invasion, cell cycle progression, drug resistance and cancer stemness." (PMID 30016974, 2018). "Subsequent studies showed that PBX3 is overexpressed in various human cancers, including prostate cancer, colorectal cancer, gastric cancer, hepatocellular carcinoma, and multiple myeloma." (PMID 30016974, 2018). "Similarly, we observed an association of HOXA9 with PBX1, PBX2, PBX3, and MEIS1 in all 10 cancer types except for STAD." (PMID 38904676, 2024).
cancer (continued). "To further delineate the upstream targets of BCAT1, we evaluated several potential signaling pathways downregulated in P2x1-null LICs, such as transcriptional misregulation in cancer, and we found that the Pbx3 mRNA level in P2x1-null LICs was significantly decreased to 10% of that in WT LICs." (PMID 36418376, 2023). "PBX3 is recognized as a crucial regulator in the invasion and metastasis in a variety of cancers." (PMID 35068042, 2022). "Therefore, PBX1 and PBX3 exhibit great potential as targets for the development of pharmacological drugs for anti‐angiogenesis in cancer treatment." (PMID 35068042, 2022). "Moreover, PBX3 has been reported as the oncogene in various human cancers, indicating its protein had the oncogenic potential." (PMID 32519740, 2020). "In addition, GO analysis and KEGG analysis showed that MAP3K2 and PBX3 participated in cancer regulation." (PMID 30765768, 2019). "As PBX3 activates MEK/ERK1/2 pathway to promote malignant phenotypes in some cancers, we hypothesized that PBX3 may promote GBM mesenchymal phenotype through MEK/ERK1/2 pathway mediated LIN28/let-7 axis activation." (PMID 30016974, 2018). "Using the expression data from the Rembrandt dataset, we performed GSEA to verify whether we could detect some hallmarks of cancer, including mesenchymal transition,in the patients with high-level of PBX3." (PMID 30016974, 2018). "Taken together, PBX3 may be a clinically relevant oncoprotein and a promising therapeutic target of these cancers." (PMID 28934982, 2017). "Information about the involvement of the PBX3 gene in cancer is nevertheless limited." (PMID 25875009, 2015). "Quantitative RT–PCR (qRT-PCR) further showed that Bcat1 (related to BCAA metabolism) or Hoxa9, Ccnt1, Pbx1, Rora and Pbx3 (related to transcriptional misregulation in cancer) were significantly reduced in P2x1-null LICs, suggesting that these genes may act as downstream targets of P2X1." (PMID 36418376, 2023). "So we could draw a conclusion that PBX3 played a cancer-promoting role as a target gene in PCa." (PMID 32519740, 2020). "However, PBX3 is mostly known as an oncogene involved in a variety of cancer types." (PMID 28957313, 2017). "Based on the average expression of PBX3, the samples in the TCGA database were divided into high and low expression groups, and the expression of PBX3 in HCC and para-cancer was drawn." (PMID 40508020, 2025). "Analysis of the HOXA9 gene revealed a positive correlation with PBX1, PBX2, PBX3, and MEIS1 in all cancer types except for STAD among the 11 studied genes, suggesting enhanced binding of HOXA9 to the promoter region of target genes." (PMID 38904676, 2024). "Let-7d directly targets c-Myc, HMGA2, CCL7, PBX3 and COL3A1, and so inhibits thereby inhibiting cancer cell invasion and metastasis." (PMID 33507713, 2021). "The HOX9-11, PBX3 and MEIS1 were also involved in the ‘Transcriptional misregulation in cancer’ pathway (KEGG database), and ‘Activation of HOX genes during differentiation’ pathway (Reactome database)." (PMID 34051812, 2021). "Among the candidate targets, PBX3, a member of the lately reported PBX family, has been described as a contributor to cancer cell proliferation and growth." (PMID 32519740, 2020). "Among them were five genes with known transcription factor activity (PBX3, HOXB3, LEF1, HOXA7, LBH) and three genes with oncogenic potential (PAPD7, PBX3, LEF1) for which a role in other cancers has been suggested previously." (PMID 32728112, 2020). "Our findings is consistent with previous reports that PBX3 functions as an oncogene and EMT enhancer in other cancers." (PMID 30016974, 2018). "Notably, six genes—MLLT3, MEIS1, PBX1, PBX3, HOXA10, KMT2A—were found to play a role in transcriptional dysregulation in cancer." (PMID 35743243, 2022). "The interaction of PBX3 and MAPK signaling was studied in several cancers." (PMID 34006845, 2021).
infection (1 paper, 2025). The state of being infected such as from the introduction of a foreign agent such as serum, vaccine, antigenic substance or organism. "Our findings showed that the downregulation of genes controlled by the transcription factors NFYA/NFYB, ZBTB7A, and PBX3 was a common feature of cells susceptible to infection both before and after exposure." (PMID 40725231, 2025). "In infection-susceptible cells, genes regulated by the transcription factors NFYA/NFYB, ZBTB7A, and PBX3 were downregulated both in the presence and absence of infection." (PMID 40725231, 2025).
respiratory disease (1 paper, 2020). "The present study found a higher incidence of respiratory disease and tumors in MPS females, suggesting both conditions may be associated with upregulated pbx3 gene expression." (PMID 32087063, 2020).